SUGP1 (SURP and G-patch domain containing 1)
Description:
Plays a role in pre-mRNA splicing.
Synonyms: SF4; F23858; DKFZp434E2216; RBP
Tractability: Small molecule: a structure with a bound ligand is known. PROTAC: ubiquitination databases record sites on it; its protein half-life has been measured.
Gene: Protein-coding gene on chromosome 19 (19,276,018 to 19,320,511, reverse strand). Ensembl gene ENSG00000105705.
Subcellular location: Nucleus
Subcellular location (Human Protein Atlas): Nucleoplasm
Pathways (Reactome):
Metabolism of RNA: mRNA Polyadenylation; mRNA Splicing - Major Pathway
Disease: Dengue Virus-Host Interactions
Gene Ontology:
Molecular function: protein binding; RNA binding; mRNA binding; nucleic acid binding
Biological process: RNA processing
Cellular component: nucleoplasm; nucleus
Genetic constraint (gnomAD): Loss-of-function variants: 34 observed, 75.13 expected, observed/expected ratio (o/e) 0.45, 90% interval 0.34 to 0.6. The upper end of that interval is the gene's LOEUF score, 0.6, which puts it in group 2 of 6, group 1 being the genes least tolerant of losing a copy. Missense variants: 752 observed, 865.07 expected, observed/expected ratio (o/e) 0.87, 90% interval 0.82 to 0.92. Synonymous variants: 326 observed, 335.02 expected, observed/expected ratio (o/e) 0.97, 90% interval 0.89 to 1.07.
Homologues: Orthologues: chimpanzee SUGP1 (99% identical), macaque SUGP1 (94% identical), pig SUGP1 (90% identical), dog SUGP1 (90% identical), mouse Sugp1 (89% identical), guinea pig SUGP1 (89% identical), rat Sugp1 (89% identical), tropical clawed frog sugp1 (63% identical), Drosophila melanogaster CG31550 (33% identical), zebrafish sugp1 (19% identical). Paralogues in human: SUGP2 (24% identical).
Diseases named in the same sentence as SUGP1 in open-access papers:
SUGP1 is named in the same sentence as 22 diseases in open-access papers, as found by Europe PMC text mining. Sharing a sentence is not in itself a finding about the gene and the disease. The quoted sentences say what the papers report.
coronary artery disease (3 papers, 2020 to 2025). "SURP and SUGP1 were associated with plasma LDL cholesterol levels, coronary artery disease and some other energy metabolism." (PMID 34769433, 2021).
dyslipidemia (2 papers, 2015 to 2020). "rs201189528 spatially connects with several other loci: SUGP1 (19p13.11), which affects serum lipid levels and dyslipidemia; LPP (3q28), which is associated with T2D in American Indians; and KCNIP3 (2q21.1), which is associated with diabetic retinopathy." (PMID 26191039, 2015). "However, the relationship between dyslipidemia and SUGP1 and MAU2 is not clear in the Chinese populations, and the association between SNPs, gene-gene, and gene-environment interactions and dyslipidemia is still limited." (PMID 32568739, 2020).
lung adenocarcinoma (2 papers, 2021 to 2022). A carcinoma that arises from the lung and is characterized by the presence of malignant glandular epithelial cells. "Our study provides definitive evidence that genetic alterations of SUGP1 genocopy SF3B1 mutations in lung adenocarcinoma and other cancers." (PMID 33057152, 2021).
migraine (2 papers, 2022 to 2023). "Among the overlapping genes, four (ADAMTSL4, EHMT2, SUGP1, and MAU2) were associated with migraine, headache, and at least five glycemic traits." (PMID 36808568, 2023).
breast carcinoma (1 paper, 2024). "Altered levels of SUGP1 have been found in a large number of uveal melanoma and breast cancer cells." (PMID 38597390, 2024).
endometrial tumors (1 paper, 2024). "This included two lung and two endometrial tumors, which are tumors where SF3B1 and related SUGP1 mutations are documented." (PMID 39390592, 2024).
hyperlipidemia (1 paper, 2020). "The genotypic and allelic frequencies of 12 SNPs in the NCAN, TM6SF2, CILP2, PBX4, SUGP1 and MAU2 were substantially different between the hyperlipidemia and normal groups." (PMID 32568739, 2020). "In conclusion, this study shows potential interactions among the NCAN, TM6SF2, CILP2, PBX4, SUGP1 and MAU2, environment and serum lipid levels in hyperlipidemia subjects." (PMID 32568739, 2020).
leukemia (1 paper, 2019). A malignant (clonal) hematologic disorder, involving hematopoietic stem cells and characterized by the presence of primitive or atypical myeloid or lymphoid cells in the bone marrow and the blood. "To further explore the clinical significance of these hub genes (SUGP1, DHX16, FUS, HNRNPR, DHX15, NAA38, SKIV2L2, and PLRG1), we used a series of online tools to evaluate the clinical expression of these hub genes in leukemia." (PMID 31766457, 2019).
lung carcinoma (1 paper, 2023). "Furthermore, SUGP1 has been recently linked to lung cancer, and PSD2 has been linked to neurological diseases according to GeneCards." (PMID 37298272, 2023).
myelodysplastic syndrome (1 paper, 2024). A clonal hematopoietic disorder characterized by dysplasia and ineffective hematopoiesis in one or more of the hematopoietic cell lines. "The role of SUGP1 is only beginning to be understood, but it was recently identified as a binding partner of SF3B1, a spliceosome component that is commonly mutated in cancers and myelodysplastic syndrome." (PMID 38880245, 2024).
sideroblastic anemia (1 paper, 2023). "Moreover, in contrast to canonical SF3B1 mutations, E592K induces a unique RNA missplicing pattern, retains an interaction with the splicing factor SUGP1, and preserves normal RNA splicing of the sideroblastic anemia genes TMEM14C and ABCB7." (PMID 37090662, 2023).
steatosis (1 paper, 2025). Increased lipid within the cytoplasm of cells. "In addition, GWAS fine mapping identified potential causal variants in GATAD2A, SUGP1, and MAU2, while TWAS fine mapping implicated SAMM50 as a driver of steatosis in normal-weight individuals, possibly through changes in gene expression." (PMID 40677695, 2025).
cancer (8 papers, 2020 to 2024). A tumor composed of atypical neoplastic, often pleomorphic cells that invade other tissues. "Mutations in the SF3B1 splicing factor gene can disrupt the interaction between the splicing factor and SUGP1, leading to splicing errors that can cause cancer." (PMID 38699234, 2024). "Pan-cancer analyses of >10,000 samples in TCGA also revealed a number of SUGP1 cancer-associated mutations flanking the SUGP1 G-patch motif (G-patch) that partially recapitulate mutant SF3B1 missplicing, suggesting a mechanistic link between SF3B1 and SUGP1." (PMID 37977822, 2023). "We have shown that numerous SUGP1 mutations affecting residues critical for binding SF3B1 recapitulate the splicing defects of hotspot SF3B1 cancer mutations, confirming the cooperative role of these two proteins in 3′ss selection." (PMID 37977822, 2023). "It is remarkable that numerous different cancer-associated mutations in SUGP1 as well as in SF3B1 function by the same mechanism; i.e., by disrupting or weakening the interaction between the two proteins." (PMID 37977822, 2023). "The loss of interaction between SF3B1 and SUGP1 due to cancer mutations in either SF3B1 or SUGP1 provides an explanation for why the mutant spliceosome fails to activate DHX15 for ATP hydrolysis required for canonical branch site selection." (PMID 37977822, 2023). "We experimentally confirmed that all the cancer-associated missense mutations in these two regions of SUGP1 weaken or abolish its interaction with SF3B1." (PMID 37977822, 2023). "An important prerequisite in understanding how SF3B1 mutations that disrupt interaction with SUGP1 cause cancer is elucidating the molecular basis underlying how these two proteins interact with each other." (PMID 37977822, 2023). "AlphaFold-Multimer modeling of the SF3B1–SUGP1 heterodimer structure revealed that two separate regions flanking the SUGP1 G-patch make numerous direct contacts with the region of SF3B1 harboring multiple hotspot cancer mutations." (PMID 37977822, 2023). "In our previous study, we identified five naturally occurring SUGP1 missense mutations (L515P, G519V, R625T, P636L, and R642W) flanking the G-patch in cancers that partially recapitulate mutant SF3B1 splicing dysregulation." (PMID 37977822, 2023). "It is the first step that mainly determines the selection of correct branch sites, consistent with the fact that all SUGP1 cancer-associated mutations (as well as additional mutations described in this study) partially recapitulate the mutant SF3B1 missplicing pattern." (PMID 37977822, 2023). "Likewise, among the five SUGP1 cancer-associated residues, only R625 and P636 were predicted to have direct interactions with SF3B1, while the other three (L515, G519, and R642) were not (although embedded in the interface)." (PMID 37977822, 2023). "Third, substitutions/deletions of the critical residues in SUGP1, including naturally occurring cancer mutations, recapitulated the RNA missplicing induced by SF3B1 cancer mutations that were previously shown to disrupt SF3B1 interaction with SUGP1." (PMID 37977822, 2023). "Two separate regions of SUGP1, including two tyrosines at the very C terminus, are essential for interaction with the region of SF3B1 that harbors cancer hotspot mutations." (PMID 37977822, 2023). "In this study, we used computational structural modeling together with experimental analyses to characterize the nature of the SF3B1–SUGP1 interaction and to elucidate the role of cancer-relevant mutations in both SF3B1 and SUGP1 in RNA missplicing." (PMID 37977822, 2023). "They further elucidate the effect of cancer-associated mutations in SF3B1 and SUGP1 that weaken their interaction, disrupting the formation of a larger complex with DHX15 and causing pre-mRNA splicing defects." (PMID 37977822, 2023). "Starting from the pan-cancer SF3B1-like 3′ss aberration pattern, we explained almost all cases either by new SF3B1 mutations outside of the known hotspots or by SUGP1 alterations." (PMID 33057152, 2021).
cancer (continued). "While it is known that SF3B1 hotspot mutations lead to loss of splicing factor SUGP1 from spliceosomes, the cancer-relevant SF3B1–SUGP1 interaction has not been characterized." (PMID 37977822, 2023). "Remarkably, all five of these SUGP1 mutations are located in the two SF3B1-interacting regions, and we thus wanted to investigate whether these cancer-associated mutations disrupt the interaction of SUGP1 with SF3B1." (PMID 37977822, 2023). "However, how SF3B1 and SUGP1 interact is not known, leaving gaps in our understanding of both how branch sites and 3′ splice sites are correctly selected and how cancer mutations disrupt this process." (PMID 37977822, 2023). "Since mutations in another splicesomal gene, SURP and G-patch domain containing 1 (SUGP1), induce aberrant splicing identical or similar to that observed in mutant SF3B1 cancers, it remains to know whether SUGP1 mutations also confer hypersensitivity to Akt inhibitors." (PMID 34419139, 2021). "DHX15, as an RNA helicase, is required for SUGP1 and participates in RNA error mediated by SF1B3 in cancer." (PMID 38699234, 2024). "Additionally, unlike both SUGP1 and DHX15, DDX46 is not known to harbor any cancer-associated mutations that recapitulate mutant SF3B1 missplicing." (PMID 37977822, 2023).
tumor (3 papers, 2016 to 2021). "However, large depletion of SUGP1 expression, often combined with SUPG1 hypomorphic variants, are not only tolerated by tumor cells but likely to be associated with the oncogenic process." (PMID 33057152, 2021). "It is worth noting that SUGP1 and PLRG1 were not available in the Oncomine databases, hinting that these two genes may have little to do with tumor cell proliferation." (PMID 31766457, 2019).
SUGP1 also shares sentences with these, for which no sentence is quoted: Alzheimer disease (1 paper); cervical cancer (1); ciliopathy (1); colitis (1); diabetes mellitus type 2 (1); diabetic retinopathy (1); neurological diseases (1); uveal melanoma (1).